ERBB2 (erb-b2 receptor tyrosine kinase 2)
Diseases named in the same sentence as ERBB2 in open-access papers (continued):
Sharing a sentence is not in itself a finding about the gene and the disease.
uterine sarcoma (7 papers, 2015 to 2025). "In summary, we herein describe the first detailed study of a novel ERBB2/ ERBB3-mutated S100/SOX10-positive unclassified highly aggressive uterine sarcoma type." (PMID 39196362, 2024). "S100/SOX10-positive uterine sarcoma with ERBB2/ERBB3 mutation is a newly recognized and highly aggressive subtype of uterine sarcoma characterized by aberrant HER2 pathway activation and neural crest-like immunophenotype." (PMID 41463261, 2025). "Lastly, a recent study introduced a novel group of uterine sarcomas with ERBB2/ERBB3 alterations which also show diffuse S100 positivity and may present as a cervical polyp." (PMID 39387892, 2024). "Similarly, another new small molecule inhibitor, CUDC-101, acts on EGFR, ERBB2, and HDAC, which are all potential targets in uterine sarcomas." (PMID 26576131, 2015). "Our Case 1 falls into this pathogenetic category and represents a novel observation in this type of uterine sarcomas, indicating that mutant ERBB3 concurrent with ERBB2 amplification represents a novel mechanism driving oncogenesis in tumors lacking the V777L ERBB2 mutation." (PMID 39196362, 2024).
uterine tumors (7 papers, 2018 to 2025). "Looking forward, we envision a future where a new algorithm for HER2/ERBB2 testing in uterine tumors is implemented, with IHC and molecular results becoming available within 7–10 days." (PMID 39682116, 2024). "A series of 7 unclassified uterine neoplasms expressing S100 and SOX10, lacking gene fusions and harboring an activating ERBB2 (HER2) mutation at codon 777 were presented in an abstract form at the USCAP annual meeting." (PMID 39196362, 2024).
ampullary adenocarcinoma (6 papers, 2015 to 2025). "Besides, we checked the correlation between EGFR/ERBB2 amplification and the prognosis of ampullary adenocarcinoma." (PMID 39762212, 2025). "HER2 (ERBB2) is altered in up to 13% of ampullary adenocarcinomas." (PMID 38136318, 2023). "Previously, ERBB2 amplification also reported in ampullary adenocarcinoma ranging from 13 to 15%." (PMID 32552660, 2020). "Although the result showed the copy number of EGFR/ERBB2 showed a worse prognosis than the low copy number patients, the results showed no statistical significance between the copy number of EGFR/ERBB2 and the prognosis of ampullary adenocarcinoma." (PMID 39762212, 2025).
Arrhythmia (6 papers, 2012 to 2023). Any cardiac rhythm other than the normal sinus rhythm. "ErbB2 transgenic mice display electrocardiographic characteristics similar to those found in patients with Hypertrophic Cardiomyopathy, with susceptibility to adrenergic-induced arrhythmias." (PMID 22912742, 2012). "Defining molecular determinants of cardiomyocyte interaction with its cellular environment, including cells and extracellular matrix, in the ErbB2 transgenic mouse may uncover new insights into myocardial disarray and mechanisms of cardiac arrhythmias." (PMID 22912742, 2012). "However, ErbB2 transgenic mice developed progressive electrocardiographic changes, including decreased R wave amplitude, widened QRS complex, and complex arrhythmias, followed by asystole and eventually death 5 to 8 minutes after isoproterenol administration." (PMID 22912742, 2012). "Although ErbB2 transgenic mice show cardiac hypertrophy-specific EKG changes, in general we did not note any arrhythmias during routine EKG recording." (PMID 22912742, 2012).
atrial fibrillation (6 papers, 2016 to 2026). A disorder characterized by an electrocardiographic finding of a supraventricular arrhythmia characterized by the replacement of consistent P waves by rapid oscillations or fibrillatory waves that vary in size, shape and timing and are accompanied by an irregular ventricular response. "Analysis of the reported AEs suggests that ibrutinib-associated atrial fibrillation is caused by binding to ERBB2/HER2 and ERBB4/HER4." (PMID 33777941, 2021). "Besides, it was found that mutations in the Erbb2 gene could impaire atrial electrical signalling; when PI3K activity is decreased, the susceptibility to atrial fibrillation was found to be increased in mouse model." (PMID 36438789, 2022). "Besides this on-target effect, ibrutinib deactivates several off-targets, e.g., EGFR, ErbB2, ITK, and TEC, which might contribute to the antitumor effect but, at the same time, result in adverse events, such as atrial fibrillation (AF) and bleeding." (PMID 37373521, 2023).
cardiac hypertrophy (6 papers, 2012 to 2022). "In neonatal, adolescent, and adult cardiomyocytes, cardiac hypertrophy is caused by induction of constitutively active ERBB2." (PMID 35211156, 2022). "By defining a role for ErbB2 in inducing cardiac hypertrophy, our results reveal new insights into previously recognized phenomena in human heart patients." (PMID 22912742, 2012). "While molecular inducers and molecular inhibitors of ErbB2 are not well understood, our animal model unequivocally for the first time establishes that activation of ErbB2 induces cardiac hypertrophy." (PMID 22912742, 2012). "The lapatinib studies were initiated to confirm the role of ErbB2 in cardiac hypertrophy." (PMID 22912742, 2012). "For example, HSP90 is a chaperone of both ErbB2 and EGFR and thus may be partially responsible for stability of these proteins in ErbB2 transgenic mice cardiac hypertrophy." (PMID 22912742, 2012). "We hypothesized that ErbB pathway inhibition would block or blunt cardiac hypertrophy initiation in mice with constitutive over-expression of ErbB2." (PMID 22912742, 2012). "Next, we used lapatinib, a pharmacological inhibitor of ErbB2 phosphorylation to induce pathway inactivation and determine whether cardiac hypertrophy in ErbB2 transgenic mice is dependent on translation pathway activation." (PMID 22912742, 2012). "Although there are marked differences in the upstream regulators of ErbB2 and myosin heavy chain, many downstream effector molecules are common and can be targeted by small-molecule inhibitors (designed initially to treat several types of cancer) to block cardiac hypertrophy." (PMID 36380187, 2022). "Furthermore, our work suggests that in the situation where ErbB2 signaling contributes to cardiac hypertrophy, inhibition of this pathway may reverse this process." (PMID 22912742, 2012). "Accordingly, cardiomyocyte-specific overexpression of ERBB2 leads to cardiac hypertrophy without heart failure." (PMID 34759299, 2021). "In humans with HCM, cardiac hypertrophy of a similar degree (as erbB2 transgenic mice) is not observed." (PMID 22912742, 2012). "ErbB2 over-expression activates and up-regulates cardiac pro-survival signaling and hypertrophic pathways, including PI3K/AKT pathway, a well-known pathway involved in increasing cardiomyocyte survival and protein translation during cardiac hypertrophy." (PMID 22912742, 2012).
coronary artery disease (6 papers, 2019 to 2026). "ERBB2 (HER2) is abundantly expressed in endothelial cells and vascular smooth muscle cells, with elevated serum HER2 levels independently associated with coronary artery disease presence and stenotic vessel number." (PMID 41544081, 2026).
endometrioid tumor (6 papers, 2010 to 2025). A benign, borderline, or malignant epithelial tumor of the female reproductive system characterized by the presence of glands and/or cysts lined by neoplastic cells that resemble endometrial cells.
endothelial dysfunction (6 papers, 2016 to 2025). In vascular diseases, endothelial dysfunction is a systemic pathological state of the endothelium (the inner lining of blood vessels) and can be broadly defined as an imbalance between vasodilating and vasoconstricting substances produced by (or acting on) the endothelium. "Perhaps inhibition of ErbB2 in endothelial cells results in endothelial dysfunction and secondary myocardial dysfunction." (PMID 27356767, 2016). "Since Nrg1 protects against endothelial dysfunction by enhancing eNOS function and ErbB2 is a receptor for Nrg1, we speculated Nrg1-ErbB2 interaction in the coronary artery endothelial cells." (PMID 34039018, 2021).
esophageal tumors (6 papers, 2017 to 2022). "Previous research showed that hsa-miR-125b (2nd in the prediction list) can promote cell proliferation in Esophageal Neoplasms by influencing the target transcripts: CYP24, ERBB2 and ERBB3." (PMID 28339468, 2017).
germ cell tumor (6 papers, 2018 to 2025). A benign or malignant, gonadal or extragonadal neoplasm that originates from germ cells. "Third, confirming whether serum levels of ERBB2 and NRG4 were elevated in these patients was not possible because patients with germ cell tumors, colitis, and acute hepatitis, for which AFP is a false positive, were not included in this study." (PMID 37174100, 2023).
Hepatic fibrosis (6 papers, 2012 to 2021). The presence of excessive fibrous connective tissue in the liver. "ErbB2 positivity of liver tissue correlated with severity of inflammation and signs of longstanding liver injury like liver fibrosis." (PMID 32591879, 2021).
liver disease (6 papers, 2019 to 2024). "In conclusion, we presented a precise characterization of liver disease associated with hepatocellular ErbB2 expression." (PMID 32591879, 2021). "Other liver diseases associated with a common ErbB2 expression were cholestatic hepatopathies and cases with subacute confluent hepatocellular necrosis following toxic injury, severe hepatocellular siderosis, and Wilson’s disease." (PMID 32591879, 2021). "Unexpectedly, we found nuclear ErbB2 expression in human hepatocytes in various liver diseases so we aimed to investigate the characteristics of liver disease leading to nuclear ErbB2 translocation." (PMID 32591879, 2021). "In alcoholic steatohepatitis and other toxic liver diseases, hepatocytes revealed a nuclear ErbB2 expression implying a so far unknown mechanism in hepatocytes upon cellular stress that might lead to resistance to cell death." (PMID 32591879, 2021). "Of note, in proximity to metastatic tumor masses, we sometimes observed some spotted ErbB2-positive hepatocytes without another underlying liver disease." (PMID 32591879, 2021). "Furthermore, analysis of hepatocellular ErbB2 expression could serve as helpful tool for diagnosis of liver disease." (PMID 32591879, 2021). "Referring to an incidental finding of hepatocellular ErbB2 expression in liver disease, we characterized ErbB2 expression in human non-tumorous and tumorous liver diseases." (PMID 32591879, 2021). "Furthermore, this study opens a wide field of research about functional implications of nuclear ErbB2 signaling deducing possible therapeutic strategies in non-neoplastic liver disease and HCC." (PMID 32591879, 2021).
Lynch syndrome (6 papers, 2018 to 2023). An autosomal dominant hereditary neoplastic syndrome characterized by the development of colorectal carcinoma and a high risk of developing endometrial carcinoma, gastric carcinoma, ovarian carcinoma, renal pelvis carcinoma, and small intestinal carcinoma. "Lynch syndrome and Lynch-like syndrome CRC frequently harbor not only activating ERBB2 mutations but also specific mutational patterns in PIK3CA and KRAS." (PMID 29849630, 2018).
papilloma (6 papers, 2017 to 2025). A benign epithelial neoplasm that projects above the surrounding epithelial surface and consists of villous or arborescent outgrowths of fibrovascular stroma. "ERBB2 is often upregulated in various cancers and in the skin ERBB2 is essential for tumor progression; its excess induces epidermal tumor initiation and spontaneous formation of papillomas." (PMID 33786987, 2021). "Thus, it cannot be excluded that a possible functional interaction of HPV8E6 with ErbB2 may contribute to the UV-induced papilloma formation." (PMID 29176966, 2017).
schwannoma (6 papers, 2013 to 2025). A benign, usually encapsulated slow growing tumor composed of Schwann cells. "ERBB2 mutation in hybrid neurofibromas and schwannomas has been proposed as a potential diagnostic and therapeutic target." (PMID 40255822, 2025). "Interestingly, previous reports have implicated overexpression of epidermal growth factor receptor family tyrosine kinases EGFR and ERBB2/HER2 in NF2-associated schwannomas and MN." (PMID 33273014, 2021). "More importantly, the NRG1 ligand and its target the ERBB family receptors have been implicated in schwannoma tumorigenesis leading to preclinical testing of EGFR/ERBB2 kinase inhibitor lapatinib in a vestibular schwannoma model." (PMID 33273014, 2021). "In human schwannomas, ErbB2 and Nrg1 expression was found to be similarly changed compared to sural nerve biopsies from healthy human individuals." (PMID 27236462, 2016). "Transcriptomic alterations, such as the neuregulin 1 (NRG1)/ErbB2 pathway, have been described in schwannomas." (PMID 23354516, 2013). "In contrast to ErbB2 and ErbB3, EGFR (another receptor of this family) was downregulated in schwannomas (−17.3-fold, p=2.26e-12)." (PMID 23354516, 2013). "Our results concur with earlier array analysis data on schwannomas, such as caveolin-1 (CAV1) downregulation, as well as with other studies conducted, using techniques such as qRT-PCR [i.e., neuregulin 1 (NRG1)-ErbB2-ErbB3 upregulation] and immunohistochemistry analysis (CCND1 upregulation)." (PMID 23354516, 2013). "Merlin, which is presumably absent in all schwannomas, has been found to block ErbB2-Src signaling." (PMID 23354516, 2013). "In schwannoma cells lacking NF2, epidermal growth factor receptor tyrosine kinases ErbB2, ErbB3 and EFGR are overabundant on the cell surface, upregulating their downstream targets, thereby driving cell proliferation." (PMID 28821767, 2017).
thymic carcinoma (6 papers, 2015 to 2026). Thymic carcinoma (TC) is a type of thymic epithelial neoplasm characterized by a high malignant potential.
thyroid tumor (6 papers, 2015 to 2025). A benign or malignant neoplasm affecting the thyroid gland. "Although the expression of ERBB2 was positively correlated with that of TSHR, the role of TSHR in radioiodine refractoriness remains debated because the highly expressed TSHR is not only associated with high radioiodine uptake but also causes fast thyroid tumor growth." (PMID 36437939, 2022).
transitional cell carcinoma (6 papers, 2005 to 2025). A malignant neoplasm arising from the transitional epithelium, usually affecting the urinary bladder, ureter, or renal pelvis.
Allergy (5 papers, 2017 to 2025). An allergy is an immune response or reaction to substances that are usually not harmful. "Some calcium signaling pathway-related genes, such as ERBB2, PDE1B, PDGFA, TPCN1, and MCU, have been reported to participate in the development of allergic diseases." (PMID 37328853, 2023). "The levels of FS (Follistatin), Erb-B2 receptor tyrosine kinase 2 (ERBB2), TGFR2 (transforming growth factor beta receptor 2), MSLN (mesothelin) and TM (thrombomodulin) were influenced by Benzodiazepines and PRS27 (serine protease 27) by allergy drugs." (PMID 37667404, 2023).
bone sarcoma (5 papers, 2017 to 2023). A sarcoma that arises from the bone. "GD2, IL-13Ra2, B7H3, and ErbB2 have been identified as potential targetable tumor antigens on solid tumors, including bone sarcomas and Ewing’s family tumors." (PMID 29029499, 2017). "Furthermore, we discovered two GAs in the ALK and BRAF genes that occurred in bone sarcomas, while three GAs in the EGFR gene and one GA in the ERBB2 gene were only found in STS." (PMID 37546405, 2023).
colitis (5 papers, 2012 to 2023). Inflammation of the colon. "Erbb2 regulates recovery from DSS-induced colitis by promoting mouse colon epithelial cell survival." (PMID 29235493, 2017).
cyst (5 papers, 2017 to 2025). A sac-like closed membranous structure that may be empty or contain fluid or amorphous material. "Interestingly, our screen did identify several HER2 (ErbB-2) inhibitors that reduced cyst swelling." (PMID 28644734, 2017). "ErbB2 (Her2) is known to be upregulated in ADPKD cells compared with normal renal epithelial cells, and treatment with ErbB2 inhibitors was found to slow cyst growth in a mouse model of ADPKD." (PMID 35979967, 2022). "In the ADPKD slices, phosphorylated EGFR was present at cyst lining epithelial cells of most cysts at the apical cell membrane, whereas phosphorylated ErbB2 was absent and phosphorylated ErbB4 was only present in some cysts (not shown)." (PMID 36914219, 2023). "Immunohistochemistry of adult biliary cysts revealed variable expression of ERBB2 in cyst epithelia and suggested that cyst formation happens in a non-proliferative way." (PMID 34413880, 2021).
hidradenocarcinoma (5 papers, 2012 to 2022). A carcinoma with apocrine and less often eccrine differentiation, arising from the sweat glands. "ERBB2 (v-erb-b2 erythroblastic leukemia viral oncogene homolog 2) gene amplification and response to trastuzumab were documented in a case of metastasizing hidradenocarcinoma." (PMID 23056620, 2012).
Infertility (5 papers, 2019 to 2025). "We evaluated the potential therapeutic value of ErbB2 as a target for correcting endometrial P4 resistance in infertility." (PMID 35232969, 2022). "To further dissect the reversal of Mig-6-related infertility by attenuation of Erbb2, we examined implantation rates." (PMID 35232969, 2022). "To address the effect of conditional Erbb2 knockout on the infertility phenotype of Mig-6d/d mice, we mated female control, Mig-6d/d, and Mig-6d/dErbb2d/d (Pgrcre/+Mig-6f/fErbb2f/f) mice with wild type male mice for 6 months to determine their overall fertility." (PMID 35232969, 2022).
liver cirrhosis (5 papers, 2019 to 2023). "Liver cirrhosis, as result of different disease conditions like ASH, revealed a mixed presentation of ErbB2 expression levels." (PMID 32591879, 2021). "Since our study focused on the prognosis of HCC, controls such as healthy controls, chronic viral hepatitis B, or liver cirrhosis were not included, and the predictive performance of our marker using ERBB2, NRG4, and MIG6 for the diagnosis of HCC could not be confirmed." (PMID 37174100, 2023).
low grade glioma (5 papers, 2018 to 2022). A grade I or grade II glioma arising from the central nervous system. "Furthermore, we identified that Caucasian CCLs in low-grade glioma (LGG) were more sensitive to irreversible tyrosine kinase inhibitors (TKI) targeting EGFR, ERBB2 or ERBB4, such as AST-1306 (Cohen’s d = 1.71, adj." (PMID 34576298, 2021).
lung disease (5 papers, 2004 to 2025). "FAM13A, ERBB2, and TCF7 are associated with lung function and various pulmonary diseases in mammals." (PMID 41190333, 2025). "Notably, we observed an elevated occurrence of the ERBB2 p.Pro1170Ala variant in oligometastatic lung disease, and an absence of PIK3CA mutations in oligometastatic liver and lung disease." (PMID 37858132, 2023).